CD4 (CD4 molecule)
Diseases named in the same sentence as CD4 in open-access papers (continued):
Sharing a sentence is not in itself a finding about the gene and the disease.
tumor (continued). "CD4-cre x IKKβfl/fl or CARMA1-KO mice do not appear to develop spontaneous tumors as they age, but this may be because the animals are kept in specific pathogen-free facilities and are not exposed to oncogeneic viruses or environmental carcinogens which may be necessary to drive tumor initiation." (PMID 25648675, 2015). "However, although 2-phenyl-4-quinolone derivatives have previously been shown to confer strong anti-tumor activity, whether these CMQ and FMQ phytocompound-derived chemicals could induce maturation of DCs and subsequently enhance CD4+ T and CD8+ T cell activities has not been reported." (PMID 21689407, 2011). "Furthermore, at the time of lung tumour growth assessment all s.c. tumours were regrowing in the PDT-treated mice depleted of CD8+ cells and those depleted of both CD8+ and CD4+ cells; however, the growth of the s.c. tumours was not inhibited in the PDT-treated mice depleted of CD4+ cells." (PMID 17505510, 2007).
infection (9,954 papers, 1996 to 2026). The state of being infected such as from the introduction of a foreign agent such as serum, vaccine, antigenic substance or organism. "Prior SARS-CoV-2 infection was associated with attenuated CD4+ recall responses, whereas infection-naïve and female participants showed the strongest functional gains." (PMID 41999211, 2026). "For double-positive SKOV3 cells, infection with all TCE-encoding oAds viruses led to a significant increase of CD69 surface expression of both CD4+ and CD8+ T cells compared to the control virus." (PMID 41552759, 2026). "The natural infection promoted by SARS-CoV-2 elicits potent CD4+ and CD8+ T lymphocyte responses commonly associated with protective antiviral immunity." (PMID 40006696, 2025). "Downregulation or loss of SAMHD1 expression augments the susceptibility of myeloid-derived cells or resting CD4 + cells to infection." (PMID 39871364, 2025). "Altogether, these results suggest that OMM12 animals show more severe body weight loss and enhanced viral clearance, associated with a stronger CD4 T cell response after systemic LCMV Cl-13 infection." (PMID 40274773, 2025). "Most common causes of death were infection (29.7%) and malignancy (28.1%).Predictors of all-cause mortality were CD4, viral load, hemoglobin level, and low BMI." (PMID 39471521, 2025). "Logistic regression identified factors associated with infection stage; linear regression assessed predictors of log10 viral load and CD4 count." (PMID 41229481, 2025). "It weakens the immune system by reducing macrophage bacterial-killing ability, suppressing CD4+ regulatory T cell production, and disrupting inflammatory signaling pathways, thereby increasing susceptibility to infection." (PMID 40556981, 2025). "HIV primarily affects CD4 T cells during an infection, causing widespread immune cell death through both direct infection and indirect (bystander) mechanisms." (PMID 41463453, 2025). "The risk of infection correlates strongly with a decline in CD4+ T-cell count, typically occurring in patients with counts below 100 cells/μL." (PMID 41209902, 2025). "For CD4 count, early infection was associated with higher log1010 CD4 (B = 0.219, 95% CI 0.124–0.313, p < 0.001), while older age predicted lower values (B = −0.008, 95% CI −0.012 to −0.004, p < 0.001)." (PMID 41229481, 2025). "Single-cell TCR analysis of three dominant SARS-CoV-2 spike-specific CD4+ T-cell responses identifies the dominant public TCRα clonotypes pairing with diverse TCRβ clonotypes that associated with mild disease at primary infection." (PMID 41034205, 2025). "Collectively, these findings demonstrate that brain CD4+ infiltrates during craniotomy infection are transcriptionally heterogenous and associated with prominent Th1- and Th17-like signatures." (PMID 39989461, 2025). "FIV infection leads to progressive depletion of CD4+ helper T cells, and in advanced stages, a loss of CD8+ cells." (PMID 41497367, 2025). "Risk factors for abnormal cytology included nadir CD4 < 200 cells/μL (aOR 2.61), prior condylomas (aOR 2.66), and infection with any oncogenic HPV genotype (aOR 4.12)." (PMID 40923874, 2025). "To this end, we used a primary CD4+ T-cell model of infection with a full-length HIV-1 molecular clone pNL4.3 mutated in the Rev open reading frame or with wild-type (wt) pNL4.349." (PMID 40021667, 2025). "HIV-1–induced cellular immunodeficiency with low CD4 cell counts is strongly associated with several infection-related and some infection-unrelated cancers among people with HIV (PWH)." (PMID 39736138, 2025). "Missingness in VL and CD4 was ~0.5% each, and the direction and magnitude of associations between infection stage and laboratory thresholds remained unchanged under extreme-bounds sensitivity analyses." (PMID 41229481, 2025).
infection (continued). "Univariable coxph analysis, incorporating all relevant co-variates, identified an association between the risk of subsequent infections and pre-treatment haemoglobin levels, as well as the pre-treatment frequencies of the C1 and H1 CD4+ clusters." (PMID 40313965, 2025). "The lack of vaccination seemed to contribute to this risk, and ambulatory patients had higher amounts of CD4+ T cells before infection compared to hospitalized patients." (PMID 41240154, 2025). "A CD4 count of 19 is classified as critically low, thereby rendering the individual highly susceptible to a variety of life-threatening infections." (PMID 40708635, 2025). "Individuals infected with HIV are more susceptible to infection with Mtb, partially attributable to the depletion of CD4+ T-cells by apoptosis induced by the viral infection, which consequently alters their effective immune response." (PMID 40431213, 2025). "F2 segregation analysis provided direct genetic evidence that MHC-II-regulated CD4+ T-cell landscapes determine neutrophil abundance before infection, a potentially important pathogenic factor in TB immunity." (PMID 40873577, 2025). "For example, cell segmentation and subsequent quantification of CD4+ T cells across inner and outer foreskin samples to assess their relative susceptibility to infection has revealed greater densities in the inner foreskin." (PMID 39854613, 2025). "M-CSF secreted by the infected cells then renders the incoming monocytes/macrophages more susceptible to infection by facilitating cell differentiation, enhancing expression of CD4, CCR5, and/or CXCR4 and potentially affecting virus replication after entry." (PMID 40507836, 2025). "Infection with the oncogenic delta-retrovirus Human T-cell Leukemia Virus Type 1 (HTLV-1) causes aggressive CD4 + T-cell malignancy or progressive neuroinflammatory disorders after a long latency period." (PMID 41071809, 2025). "We observed that increased frequencies of CD4 CM and CD4 EM TIGIT+ T cells pre-transplant were associated with infection (p=0.014 and p=0.018, respectively), even with age correction (Pre)." (PMID 40475763, 2025). "This inhibition renders CD4+ T-cells less susceptible to subsequent infection by HIV-1 during contemporaneous HIV-1 superinfection." (PMID 40687432, 2025). "IN immunisation was associated with fewer total cells in the lung following infection, but an increase in both CD4 and CD8 Trm." (PMID 40615441, 2025). "We found that mDCs tended to have increased the expression of DC-SIGN in S2 of AHI, increasing their potential to cause trans-infection of HIV-specific CD4+ T cells." (PMID 39932316, 2025). "In summary, we observed alterations in CD4+ T cell memory subsets that were associated with SARS-CoV-2 specific T cell responses more than 250 days post-infection." (PMID 40498720, 2025). "The decrease in GATA‐3 expression is unlikely to be due to a loss of Th2 cells, as 20–60% of the PleC CD4+ T cells remain IL‐4gfp+ Th2 cells during the hypo‐responsive phase of infection." (PMID 40755147, 2025). "Transcriptomic and protein-level analyses revealed that PDCD1 (encoding PD-1) was significantly upregulated in CD4+ T cells from AG ferrets at baseline and during infection, indicating a pre-existing exhaustion phenotype." (PMID 40794649, 2025). "While CD8+ cytotoxic T lymphocytes (CTLs) and CD4+ helper T cells are essential for clearing viruses, faulty T cell responses, especially during secondary infections, can cause a cytokine storm and damage tissues." (PMID 41305369, 2025). "Due to their susceptibility to infection, these new recruits contribute to the majority of the CD4 T-cell depletion observed during acute infection by sustaining a vicious cycle of inflammation, viral replication, and additional cell death." (PMID 41463453, 2025).
infection (continued). "The results revealed greater numbers of Pank4-deficient (CD45.1-CD45.2+) CD4+ T cells in both the lungs and mediastinal lymph nodes 5 days post infection than did wild-type (CD45.1+CD45.2+) CD4+ T cells." (PMID 40962808, 2025). "Patients with uncontrolled viral loads or CD4 counts below 200 cells/mm3 are more susceptible to surgical site infections, impaired wound healing, and delayed recovery due to persistent immune dysfunction, chronic inflammation, and nutritional compromise." (PMID 40732042, 2025). "Recent infection has been linked to better immunological status because CD4 depletion is minimal during the initial months of infection." (PMID 41229481, 2025). "Older age predicted higher viral load and lower CD4 count, whereas recent infection was associated with better immunological status." (PMID 41229481, 2025). "Correlation analysis with multiple parameters including sex, weight, and cellular immune responses in the lungs revealed that enhanced control of infection is associated with increased numbers of CD4 T cells, CD8 T cells, and B cells." (PMID 40937719, 2025). "used cut-offs of 200/μL at three months for CD4+ T-cells by extrapolating data of infection risk from HIV literature." (PMID 40607432, 2025). "Leishmania infection in GPX4-deficient mice leads to a reduction in the number of CD4+ T cells, which contributes to the establishment of infection." (PMID 40667873, 2025). "Infection with S. aureus or C. albicans causes kidney CD4+ TRM cells to adopt an inflammatory Th17 phenotype, exacerbating the disease." (PMID 39802636, 2025). "A CD4+ cell count ≥ 500 cells/mm3 was linked to a lower risk of infection with both high- and low-risk HPV genotypes." (PMID 40872859, 2025). "Lower levels of CD4 CM T cells (<15.8%) were significantly associated with freedom from infection with an HR of 2.9 (95% CI 1.4-5.8) (p=0.003)." (PMID 40475763, 2025). "We found that adoptive transfer of WT or IFN-γ-deficient CD4+ T cells into Tcra–/– hosts produced a similar degree of Mtb control in the lungs at 4 weeks post-infection." (PMID 40489538, 2025). "In individuals with CD4 counts below 200 cells/μL, the risk of post-operative infections and complications is significantly elevated." (PMID 40732042, 2025). "Peak viremia at approximately day 7–10 of infection is associated with substantial CD4+ depletion, particularly in gut tissues." (PMID 40464563, 2025). "Expansion of IL-17+CD4+ T cells is also associated with intestinal immunopathology during infection." (PMID 40590563, 2025). "Although CD8 + T cells are the primary phenotype found in the brain under infection, the initiation of CNS infection is mostly caused by CD4 + T cells." (PMID 40386405, 2025). "The acute phase of infection is marked by rapid viral replication and massive CD4+ T cell depletion in gut-associated lymphoid tissue." (PMID 41009690, 2025). "Increased frequency of total or CD25+ CD4+ CM T cells, in contrast, was associated with development of infection (p=0.033 and p=0.032, respectively)." (PMID 40475763, 2025). "Analysis of Tregs also showed a significant association, with increased CD4 CM T regs post-transplantation associated with infection (p=0.038)." (PMID 40475763, 2025). "Increased frequency of EM TIGIT+ CD4 T cells demonstrated a trend towards association with infection (p=0.18)." (PMID 40475763, 2025). "The CD4+ Th cell subpopulation associated with a reduced risk of grade ≥3 infection also expressed activation markers ICOS and HLA-DR, supporting the idea that these cells were primed and activated for a Th1 response." (PMID 40313965, 2025). "CD4-depleted infected μMT-/- mice exhibited reduced IL-10 and rapid weight loss, succumbing to infection by day 6 after CD4 neutralization." (PMID 40972121, 2025). "Compared to LCs, epidermal CD11c+ DCs were more efficient at HIV uptake and more susceptible to infection and correspondingly efficient at mediating both first-phase and second-phase transfer to CD4 T cells." (PMID 39861894, 2025).
infection (continued). "To extend the finding that specific T cell phenotypes were associated with infection, we determined cutoffs predictive of infection for several key CD4 T cell subtypes." (PMID 40475763, 2025). "In vivo, M. tb-infected CD137L-deficient mice showed delayed activation of CD4+ T cells in mediastinal lymph nodes (MLNs) at 3 weeks post-infection, followed by significantly higher frequencies of activated CD4+ T cells at weeks 10 and 14 compared to WT mice." (PMID 41256867, 2025). "In this large cohort of people living with HIV in South Africa, HIV-1 viremia was associated with an increased risk of most infection-related cancers and some infection-unrelated cancers both before and after adjusting for CD4 cell count." (PMID 39736138, 2025). "IL-10 induction during Sa infection is associated with the inhibition of protective CD4+ T cell development, allowing for Sa reinfections." (PMID 39680460, 2024). "Following infection of Jurkat CD4+ T cells with RGH, treatment with CBP/p300 inhibitors caused an increase in the proportion of productive infections and resulted in a significant increase in expression from the 5′ LTR." (PMID 39640574, 2024). "Morbidity and mortality in infection with the species Schistosoma mansoni are due to a pathogenic CD4 T cell-mediated immune response directed against parasite eggs, resulting in granulomatous inflammation." (PMID 38559160, 2024). "The donor individual would need to have CD4 alleles that yield high titers of SIV in its body, and the recipient individual would need to have CD4 alleles that make it receptive to infection by this new virus." (PMID 38014262, 2024). "al showing that transfer of IFN-γ-deficient CD4 T cells into TCRβ-deficient mice was sufficient to control FRT infection and protect mice from fatal infection." (PMID 38166152, 2024). "In female-to-male and MSM-insertive transmissions, the time to a clinically significant recipient CD4+ T cell count for infections initiated by a single variant (9.78, 9.95) was actually slightly shorter than those initiated by multiple variants (9.93, 9.97)." (PMID 39471873, 2024). "For HIV-1, infections initiated by multiple genetically distinct viral variants are associated with elevated set point viral loads (SpVL) and faster CD4+ T cell decline, which are indicative of a faster progression to AIDS when left untreated." (PMID 39471873, 2024). "Because the discriminatory lesion was rich in lymphocytes and CD4 T cell-mediated immunity is required for resistance, we expected CD4 T-cell genes would be elevated in asymptomatic infection." (PMID 38899881, 2024). "The ART adherence, educational status, HAART durations, WHO clinical stages, and CD4+ T cell levels were the major risk factors identified for the infection of TB among PLHIV." (PMID 40809574, 2024). "Human immunodeficiency virus infected patients with impaired Th1 cell immunity and low CD4+ counts are highly susceptible to S. aureus and have more invasive infections and a higher recurrence rate than patients with intact T cell immunity." (PMID 38969796, 2024). "Our model framework revealed we should not expect a high probability of multiple variants initiating infection to coincide with high log10 SpVL and a faster rate of CD4+ T cell decline." (PMID 39471873, 2024). "Our findings indicate that age over 30, divorced/widowed, peasant, heterosexual infection, CRF01_AE, long-term infection, and Pre-treatment Viral load >10000 copies/ml were factors associated with higher risk for pre-treatment CD4+T lymphocyte decline." (PMID 38994006, 2024). "Previous observations linking multiple variant infection to a higher SpVL and faster rate of CD4+ T cell decline are inconsistent." (PMID 39471873, 2024). "Different literature stated that a high viral load can lead to a low CD4 cell count which in turn increases the risk of developing an illness or infection." (PMID 38980874, 2024).